CNTNAP3 (contactin associated protein family member 3)
Synonyms: CASPR3; KIAA1714; FLJ14195; CNTNAP3A
Tractability: Antibody: UniProt places it where antibodies can reach, with high confidence; UniProt predicts a signal peptide or a membrane-spanning region; its Gene Ontology location is reachable by antibodies, with medium confidence. PROTAC: its protein half-life has been measured.
Gene: Protein-coding gene on chromosome 9 (39,064,710 to 39,288,611, reverse strand). Ensembl gene ENSG00000106714.
Subcellular location: Cell membrane (Isoform 1); Secreted (Isoform 2)
Gene Ontology:
Biological process: cell recognition; nervous system development; signal transduction
Cellular component: membrane; plasma membrane; synapse; extracellular region
Genetic constraint (gnomAD): Loss-of-function variants: 33 observed, 60.25 expected, observed/expected ratio (o/e) 0.55, 90% interval 0.41 to 0.73. The upper end of that interval is the gene's LOEUF score, 0.73, which puts it in group 2 of 6, group 1 being the genes least tolerant of losing a copy. Missense variants: 506 observed, 668.68 expected, observed/expected ratio (o/e) 0.76, 90% interval 0.7 to 0.81. Synonymous variants: 216 observed, 252.96 expected, observed/expected ratio (o/e) 0.85, 90% interval 0.76 to 0.96.
Homologues: Orthologues: chimpanzee CNTNAP3 (82% identical), rat Cntnap3 (74% identical), mouse Cntnap3 (74% identical), tropical clawed frog cntnap4 (58% identical), zebrafish cntnap3 (51% identical). Paralogues in human: CNTNAP3B (98% identical), CNTNAP4 (70% identical), CNTNAP5 (53% identical), CNTNAP2 (47% identical), CNTNAP3C (38% identical), CNTNAP1 (37% identical), NRXN2 (25% identical), NRXN3 (23% identical), NRXN1 (22% identical), CUBN (17% identical), HEPH (14% identical), HEPHL1 (14% identical), and 23 more.
Diseases named in the same sentence as CNTNAP3 in open-access papers:
CNTNAP3 is named in the same sentence as 11 diseases in open-access papers, as found by Europe PMC text mining. Sharing a sentence is not in itself a finding about the gene and the disease. The quoted sentences say what the papers report.
depression (3 papers, 2021 to 2025). "The results showed that Cntnap3 knockdown reduced anxiety‐ and depression‐like behaviors, as evidenced by decreased jump counts in the OFT and reduced immobility duration in the FST." (PMID 40911142, 2025). "The results indicated that the dysregulation of CNTNAP3 might affect brain function and consequently influence the onset of depression." (PMID 35328018, 2022). "However, the relationship between CNTNAP3 and depression has rarely been studied." (PMID 35328018, 2022).
alcohol dependence (1 paper, 2025). Physical and psychological dependence on alcohol. "Taken together, CNTNAP3 may be a candidate gene for alcohol dependence." (PMID 40730494, 2025).
alcohol use disorder (1 paper, 2025). "Whole‐exome sequencing of 83 alcohol use disorder patients identified 106,525 SNVs and 19,826 InDels, revealing six genes (CNTNAP3, ZNF683, ALDH2, CCHCR1, ZNF45, ESRRA) with deleterious mutations through comprehensive bioinformatics analysis." (PMID 40730494, 2025).
Crohn disease (1 paper, 2015). A gastrointestinal disorder characterized by chronic inflammation involving all layers of the intestinal wall, noncaseating granulomas affecting the intestinal wall and regional lymph nodes, and transmural fibrosis. "This phenomenon showed that ATG16L1 played an important role in the course of the disease, and the relationship between ATG16L1 and CNTNAP3 showed that CNTNAP3 might be of importance in autophagy process of Crohn's disease." (PMID 25883416, 2015). "In our study, we found CNTNAP3 was highly expressed in colonic samples from Crohn's disease patients, and it might increase the autophagy process in cell models." (PMID 25883416, 2015).
schizophrenia (1 paper, 2022). A major psychotic disorder characterized by abnormalities in the perception or expression of reality. "The dysregulation of CNTNAP3 was found to be linked to neurocircuit impairment in schizophrenia patients’ brains." (PMID 35328018, 2022).
stomach carcinoma (1 paper, 2022). "Further bioinformatics analysis of the ASCL2 in STAD patients using the cBioPortal and GEPIA system shows that the ASCL2 may be related to CNTNAP3, CLIP1, C9orf84, ARIH2, and IL1R2 mutations and involved in stomach carcinoma prognosis, which requires further verification in future studies." (PMID 36008864, 2022).
viral infection (1 paper, 2021). "CNTNAP3B, like CNTNAP3, is a cell-recognition molecule mediating glial cell contacts and has not been identified as part of the host response to viral infection." (PMID 34777354, 2021).
psychiatric disorder (2 papers, 2022 to 2025). A disorder characterized by behavioral and/or psychological abnormalities, often accompanied by physical symptoms. "This variant link noncoding genetic variation to psychiatric disease risk by modulating PAXIP1‐AS1 and CNTNAP3 expression, with downstream impacts on synaptic function and behavior." (PMID 40911142, 2025). "CNTNAP3, a member of the CASPR (contactin associated protein) family, has been found to be associated with several psychiatric disorders in prior studies." (PMID 35328018, 2022). "Additionally, dysregulation of these TFs in psychiatric disorders may further impact PAXIP1‐AS1 and CNTNAP3 expression, linking this regulatory variant to neuropsychiatric disease risk." (PMID 40911142, 2025).
neurodevelopmental disorder (1 paper, 2023). A behavioral and cognitive disorder with onset during the developmental period that involves impaired or aberrant development of intellectual, motor, or social functions. "It would also be of great interest to conduct similar studies for other members of the Contactin Associated Protein family, which have also been associated with neurodevelopmental disorders such as ASD, especially Caspr3/CNTNAP3, Caspr4/CNTNAP4, and Caspr5/CNTNAP5." (PMID 36793543, 2023).
CNTNAP3 also shares sentences with these, for which no sentence is quoted: Anxiety (2 papers); epilepsy (1).